ALG3 (ALG3 alpha-1,3- mannosyltransferase)
Diseases named in the same sentence as ALG3 in open-access papers (continued):
Sharing a sentence is not in itself a finding about the gene and the disease.
neurodevelopmental disorder (1 paper, 2021). A behavioral and cognitive disorder with onset during the developmental period that involves impaired or aberrant development of intellectual, motor, or social functions. "In the case of CDG with the primary neurological phenotype (neurodevelopmental disorders), including ALG1-CDG, ALG3-CDG, ALG13-CDG, and DPAGT1-CDG, liver is affected in a minority of patients." (PMID 34291020, 2021).
skeletal dysplasia (1 paper, 2021). Any Mendelian diseases that affects growth and development of the skeleton. "In some of them (ALG12-CDG, ALG3-CDG, ALG9-CDG, PGM3-CDG, SLC35D1-CDG), a severe prenatal-onset skeletal dysplasia was observed and associated with an early death." (PMID 34441372, 2021). "Contrary to PMM2-CDG, all remaining CDG, including ALG12-CDG, ALG3-CDG, ALG9-CDG, ALG6-CDG, PGM3-CDG, CSGALNACT1-CDG, SLC35D1-CDG and TMEM-165, are characterized by well-defined skeletal dysplasia." (PMID 34441372, 2021). "There is a group of CDGs, including ALG12-CDG, ALG3-CDG, ALG9-CDG, ALG6-CDG, PGM3-CDG, CSGALNACT1-CDG, SLC35D1-CDG, and TMEM-165 with well-defined skeletal dysplasia." (PMID 34441372, 2021). "Contrary to PMM2-CDG, skeletal dysplasia was well characterized in other CDGs, including ALG12-CDG, ALG3-CDG, ALG9-CDG, ALG6-CDG, PGM3-CDG, CSGALNACT1-CDG, SLC35D1-CDG and TMEM165-CDG." (PMID 34441372, 2021).
ALG3 also shares sentences with these, for which no sentence is quoted: cervical cancer (4 papers); bladder cancer (2); lung adenocarcinoma (2); cervical squamous cell carcinoma (1); cholangiocarcinoma (1); cholesteryl ester storage disease (1); colon adenocarcinoma (1); cutis laxa (1); dilated cardiomyopathy (1); endometrial carcinoma (1); eosinophilic esophagitis (1); esophageal carcinoma (1); Fabry disease (1); fructose intolerance (1); gastric adenocarcinoma (1); Gaucher disease (1); glioblastoma (1); head and neck squamous cell carcinoma (1); microcephaly (1); nasopharyngeal carcinoma (1); oral squamous cell carcinoma (1); pheochromocytoma (1); polycystic ovaries (1); prostate adenocarcinoma (1); psoriasis (1); rectal adenocarcinoma (1); sensorineural hearing loss (1); steatosis (1); Wolman disease (1).